POSTN (periostin)
Diseases named in the same sentence as POSTN in open-access papers (continued):
Sharing a sentence is not in itself a finding about the gene and the disease.
tumor (continued). "We observed that periostin was localized predominantly at tumor stroma, including the ECM and the cytoplasm of CAFs and less expressed on the cancer cells." (PMID 39941916, 2025). "POSTN knockout (Postn−/−) mice exhibited reduced infiltration of PD-1-positive TAMs in CRC tumours and displayed a lower tumorigenic potential." (PMID 39780187, 2025). "To assess the impact of the POSTN-NOTCH1 axis on SCLC tumor growth, we established a subcutaneous xenograft model in BALB/c-nu/nu mice by co-injecting SCLC cells (H128) and HSCs (LX-2), in a 1:3 ratio." (PMID 39762921, 2025). "The mechanism of POSTN mediated HSC activation in HCC TME mainly includes three pathways: (A) Tumor cell-derived TGF-β induces POSTN expression in HSCs via the suppressor of mother against decapentaplegic (SMAD) pathway." (PMID 41018265, 2025). "Since HCC is a complex disease, we should pay attention not only to the abnormal expression of POSTN inside tumor cells, but also to the POSTN protein secreted by CAFs." (PMID 41018265, 2025). "The upregulation of POSTN in our tumor-derived mCAF cluster resonates with reports that POSTN+ CAFs as potent immune response barriers at specific tumor locations, as they hinder effective T-cell infiltration and decrease the efficacy of immunotherapy." (PMID 41346635, 2025). "Periostin is an important regulator of bone, cardiac development, and wound healing, playing an important role in tumor development and being upregulated in different cancers." (PMID 41302034, 2025). "Periostin, a matricellular protein, was reported to be expressed on both cancer cells and surrounding tumor stromal cells, such as CAFs, and is regulated by Smad2/3 signaling." (PMID 39941916, 2025). "Our findings underscore that POSTN amplification facilitates tumor metastasis through intricate crosstalk between SCLC cancer cells and HSCs." (PMID 39762921, 2025). "Tumor samples were classified into high- and low-POSTN expression groups based on the 75th percentile of fibroblast-derived POSTN expression." (PMID 40520021, 2025). "In this study, we identified the POSTN-ITGAV/ITGB5 axis as a tumor-promoting signaling axis that mediates crosstalk between ECM-remodeling fibroblasts and EMT-associated epithelial cells." (PMID 40520021, 2025). "POSTN knockdown in combination of NOTCH inhibitor DAPT led to synergistic tumor growth regression compared with monotherapy." (PMID 39762921, 2025). "The antibodies of POSTN inhibit tumor proliferation and induce tumor necrosis, further, it can suppress the migration to the bone." (PMID 39947253, 2025). "One research study demonstrated the involvement of periostin, an extracellular matrix protein with multifunctional roles in inflammatory conditions and tumor spread." (PMID 39936032, 2025). "POSTN expression increased proportionally with tumor size (pT), histological grade (G), and lymph node involvement (pN)." (PMID 39272978, 2024). "Their studies have demonstrated that the upregulation of CTHRC1, VCAN, and POSTN plays a pivotal role in the initiation of angiogenesis, hence facilitating the provision of essential nutrients to tumor cells." (PMID 38420016, 2024). "Cell proliferation assay showed similar results that integrin neutralizing antibodies αvβ3 and αvβ5 reversed the elevated proliferative ability of tumor cells induced by POSTN." (PMID 38773979, 2024). "Univariate and multivariate survival analysis according to tumor characteristics and combined expression of platelet-derived growth factor receptor beta (PDGFRb), periostin and α-smooth muscle actin (α-SMA)." (PMID 38328551, 2024). "Accordingly, knockout of periostin in GSCs significantly reduces TAMs infiltration, inhibits tumor growth, and increases survival in mice with GSCs-derived xenografts." (PMID 38969910, 2024). "The third and the most important discovery was the reprogramming role of cellular interaction between SPP1+ macrophages and POSTN+ fibroblasts and tumor cells, thus reshaping the desmoplastic TME." (PMID 38519500, 2024).
tumor (continued). "We uncover a feedback loop involving tumor cell-derived IL-4 and CAF-derived POSTN, which highlights the intricate crosstalk between tumor cells and their microenvironment." (PMID 38773979, 2024). "POSTN exon 17 antibodies significantly inhibited primary tumor growth in a dose-dependent manner (p < 0.05), as well as lung metastasis (p < 0.05)." (PMID 39272982, 2024). "Periostin has been shown to interact with tumor cells and promote cell proliferation, migration, survival, epithelial-mesenchymal transition, and contribute to distant metastasis." (PMID 38279150, 2024). "In contrast, during angiogenesis, the tip cell secretes Transforming Growth Factor Beta 1 (TGF-β1) and periostin, allowing reactivation of the dormant tumor cells, their proliferation, and metastatic development." (PMID 39682261, 2024). "POSTN is an extracellular matrix protein (ECM) that is essential for EMT in a variety of tumour cells." (PMID 38280891, 2024). "A small interfering RNA (siRNA) can be used to downregulated the periostin gene, while sustained release of gemcitabine can promote killing of tumor cells." (PMID 38706910, 2024). "In agreement with in vitro data, tumor volume and weight were inhibited by IR treatment or circ‐POSTN knockdown, while this effect was significantly enhanced in mice with circ‐POSTN silence and IR treatment." (PMID 38553795, 2024). "The analysis also showed that pT2 and pT4 tumors showed a similar pattern of a high POSTN expression in tumor cells in relation to pT1 tumors (** p < 0.01)." (PMID 39272978, 2024). "Our study reveals a key role for POSTN in the tumor microenvironment in polarizing macrophages toward a pro-tumorigenic phenotype." (PMID 38942020, 2024). "Specifically, Periostin has been shown to interact with tumour cells through integrin receptors, contributing to processes such as cell proliferation and migration." (PMID 38892298, 2024). "Periostin (encoded by the POSTN gene) is an ECM protein secreted by CAFs and involved in tumor microenvironment remodeling during tumor progression." (PMID 38389400, 2024). "To explore the contribution of periostin to the pathogenesis of AD, we initially conducted a comparative analysis of periostin expression in skin lesions obtained from AD-afflicted mice." (PMID 39722037, 2024). "This provides a molecular explanation for periostin pro-survival role in tumor progression by facilitating angiogenesis and the formation of metastatic colonies." (PMID 39682261, 2024). "Survival analysis of these patients with NSCLC showed that those with a high expression of POSTN in their cancer cells and tumor stroma were characterized by significantly shorter survival compared to patients showing a low expression of this glycoprotein." (PMID 39272978, 2024). "POSTN has been demonstrated to control various biological aspects of tumor cells, including proliferation, invasion, survival, angiogenesis, metastasis, and resistance to chemotherapy." (PMID 39195230, 2024). "Through cell experiments, we found hat overexpression of FN1 and POSTN in CAFs significantly promoted the wound healing and invasion ability of tumor cells." (PMID 38601538, 2024). "Our findings suggest that the crosstalk between CAFs and tumor cells via POSTN and IL-4 plays an important role in papillary thyroid tumor progression." (PMID 38773979, 2024). "In this study, we revealed that POSTN is predominantly derived from CAFs in papillary thyroid tumors and POSTN deficiency in CAFs impairs CAF-promoted tumor growth." (PMID 38773979, 2024). "POSTN has been shown to regulate multiple biological behaviors of tumor cells and to exert a pivotal role in remodeling various tumor microenvironments." (PMID 38347567, 2024). "Intriguingly, expression of MDK and POSTN increased with time in biopsies from tumor 4, correlating with the switch from therapeutic response to resistance formation in this patient." (PMID 38942020, 2024).
tumor (continued). "Multiplex immunofluorescence staining assays further revealed that IL-4 was well colocalization with cancer cell marker EpCAM and POSTN was mainly distributed in tumor stroma." (PMID 38773979, 2024). "Our results regarding EPHB2 and LGR5 stem-cell signatures support the importance of periostin for cancer stem-cell niches at the pericryptal regions for tumour development." (PMID 38532103, 2024). "Our findings underscore the enhanced proliferative capacity of tumor cells in the leading‐edge area, juxtaposed with a distribution that interfaces closely with stromal elements such as endothelial cells and POSTN+ fibroblasts." (PMID 39716897, 2024). "Isolated mouse CAFs exhibited higher levels of POSTN protein and mRNA compared to isolated tumor cells." (PMID 38773979, 2024). "Meanwhile, CAF-derived periostin endorses the tumor progression, metastasis, and cancer-stem cells (CSC) phenotype through the canonical Wnt/β-catenin axis in the head and neck squamous cell cancer." (PMID 38361941, 2024). "Considering that in many tumors, the CD70 protein is also overexpressed by the tumor cells themselves, we further studied the effect of POSTN on the CD70 level in GSCs." (PMID 39227950, 2024). "Previous studies on a larger number of cases of NSCLC assessed the expression of POSTN in tumor cells and CAFs." (PMID 39272978, 2024). "HE staining and immunohistochemical analysis revealed that POSTN knockdown reduced tumor growth and the expression of β-catenin and FOSL1, the GSC marker CD133, and the proliferation marker Ki67." (PMID 39227950, 2024). "The aim of this study was to determine the relationship between POSTN expression (in tumor cells [NSCLC cells] and the tumor stroma) and pro-angiogenic factors (CD31, CD34, CD105, and VEGF-A) and microvascular density (MVD) in NSCLC." (PMID 39272978, 2024). "POSTN is a gene involved in tumorigenesis, the modulation of the tumor microenvironment, intravascular tumor dissemination and metastases." (PMID 39064815, 2024). "ALK contributes to tumor growth by upregulating the extracellular matrix protein periostin and activating WNT signaling." (PMID 38451815, 2024). "In turn, tumor cell-derived IL-4 induces the activation of CAFs and stimulates POSTN expression by activating STAT6." (PMID 38773979, 2024). "Conversely, treatment of MYCN tumor cells with the GSK3β inhibitor CHIR99021 (WNT activator) increased periostin." (PMID 38451815, 2024). "Published data also suggest that the level of POSTN indicates accelerated tumor progression, neovascularization, and lymphangiogenesis, as well as a worse prognosis for NSCLC patients." (PMID 39329988, 2024). "Bioluminescence imaging on days 7, 14, 21, and 28 revealed that POSTN depletion significantly inhibited tumor growth and prolonged the survival of tumor-bearing mice." (PMID 39227950, 2024). "Pancreatic stellate cells (PSCs) play a crucial role in this microenvironment and specially secrete periosteal protein (periostin), which can promote tumor growth, metastasis, and chemoresistance." (PMID 38706910, 2024). "Our study found a statistically significant positive correlation between POSTN expression in cancer cells and its expression in the tumor stroma (CAFs) in the entire group of patients and in the histological subtypes analyzed separately (SCC, AC, and LCC)." (PMID 39272978, 2024). "Immunohistochemical staining showed that POSTN was significantly elevated in tumor-bearing mice compared to control mice." (PMID 38773979, 2024). "Collectively, these data suggest that POSTN promotes proliferation and IL-4 production in tumor cells through the integrin-FAK-STAT3 signaling." (PMID 38773979, 2024). "Silencing POSTN expression in GSCs reduced the recruitment of TAMs, inhibited tumor growth and increased the survival rate of mice transplanted with GSCs." (PMID 39227950, 2024).
tumor (continued). "In the NSCLC group, a significantly higher level of POSTN expression was demonstrated in the tumor cells and stroma of pT3 tumors compared to pT1 tumors (*** p < 0.001)." (PMID 39272978, 2024). "Our mIHC results also demonstrated that the fibroblast marker, Collagen I, is distributed on both sides of the L area, while POSTN+ CAFs are found only on the tumor side, corroborating our findings from single‐cell and spatial transcriptomics studies." (PMID 39716897, 2024). "ST deconvolution and ISS projection confirmed that the expanded POSTN+ fibroblasts were localized in proximity to tumour islands." (PMID 38165934, 2024). "In a cardiac remodeling mouse model that showed enhanced tumor growth, both cardiac tissues and plasma levels of periostin were reported to be increased, and an in vitro study demonstrated its role in tumor cell proliferation." (PMID 38279150, 2024). "We have succeeded for the first time in specifically staining splicing variants of POSTN mRNA, especially pathological splicing variants including exon 21, on the pathology of the HSC-3 xenograft model primary tumor." (PMID 39195230, 2024). "Altogether, circ‐POSTN silence limited tumor growth and enhanced radiosensitivity in EC cells by regulating the miR‐876‐5p/FYN axis in vivo." (PMID 38553795, 2024). "A significant increase of tumor burden and weight was found in mice co-injected with tumor cells and WT CAFs compared with tumor cells alone, whereas POSTN depletion in co-injected CAFs significantly impaired the CAF-promoted growth of papillary thyroid tumor." (PMID 38773979, 2024). "POSTN is predominantly expressed and secreted by activated PSCs or CAFs,10 suggesting that POSTN‐positive PSCs and CAFs can play an important role in remodeling the tumor immune microenvironment." (PMID 38389400, 2024). "Here, we showed for the first time that the inhibition of periostin increased the infiltration of cytotoxic NK-92 cells into tumor-mimicking spheroid structures." (PMID 36830807, 2023). "Here, we report that high stromal expression of POSTN detected by IHC identifies CMS4 patients, associates with increased TGF-beta activity and predicts worse outcome independently of the tumor stromal load." (PMID 36765091, 2023). "By analyzing using bulk RNA‐seq data (TCGA‐HNSC), POSTN expression in tumor tissues was lower than that in normal tissues." (PMID 36691359, 2023). "Periostin changes the tumor microenvironments and plays multiple roles in tumor initiation, progression, and metastasis." (PMID 36598904, 2023). "IHC of VHL and POSTN in serial sections of the primary tumor of case #22 showed that VHL+ areas were POSTN negative (POSTN−) whereas VHL− areas stained positive for POSTN (POSTN+)." (PMID 37069149, 2023). "Previous studies suggested that periostin expression in OC cells promotes intraperitoneal tumor metastatic growth in immunodeficient mice." (PMID 38049490, 2023). "By focusing on three matrix components typically up-regulated in the tumor microenvironment (TME) of iCCA (POSTN, TnC, and OPN), we also evaluated their effects on the biology of iCCA cells." (PMID 36902188, 2023). "This study clarifies the significance of the secreted protein periostin in mediating communication between TNBCs and the surrounding adipocytes within the tumor microenvironment." (PMID 37716956, 2023). "CIBERSORT algorithm and Tumor Immune Estimation Resource (TIMER) were used to elucidate the association of SPOCK1 and POSTN expression with immune cell infiltration level." (PMID 36611136, 2023). "POSTN is also an essential factor for macrophage recruitment in the tumor microenvironment and is involved in the interactions between macrophages and cancer cells." (PMID 37709737, 2023). "Two myCAF subclusters with high expression of POSTN, C02_POSTN and C07_MKI67, were mostly involved in biological functions promoting tumour progression, such as EMT and angiogenesis." (PMID 38115703, 2023).
tumor (continued). "We used a xenograft mouse model of serous epithelial OC to determine if exogenous periostin contributes to tumor formation in vivo." (PMID 38049490, 2023). "In vivo, OC cells cultured with higher exogenous periostin showed more aggressive tumor formation relative to control cells." (PMID 38049490, 2023). "A subcluster of myofibroblastic CAFs, POSTN+ CAFs, were significantly enriched in advanced tumours and presented gene expression signatures related to extracellular matrix remodeling, tumour invasion pathways and immune suppression." (PMID 38115703, 2023). "Our results support previous findings suggesting periostin as an important factor in recruiting macrophages in the tumor microenvironment." (PMID 37531393, 2023). "Subcluster mFibro accounted for the majority of the fibroblast populations in tumor tissue and expressed a high level of COL1A1, MMP11, FN1 and POSTN, which were associated with collagen secretion and extracellular matrix modeling." (PMID 37265785, 2023). "Further analysis revealed that periostin boosted the tumor stem cell (CSC)-like phenotype through PTK7-Wnt/β-catenin signaling, inducing HNSCC cell migration in vitro." (PMID 37055382, 2023). "In NSCLC, FAP+aSMA+CAFs, which prevent T-cell contact with tumour cells, are also characterized by high expression levels of POSTN." (PMID 37199594, 2023). "By CIBERSORTx analysis in TCGA‐NSCLC samples, we also found that POSTN+ CAFs significantly enriched in tumour samples at either advanced TNM stages or T stages." (PMID 38115703, 2023). "In this study, we initially examined the role of Periostin in cardiac-remodeling-dependent tumor-promotion using Periostin knockout mice (KO)." (PMID 38139195, 2023). "We first confirmed the existence of POSTN+FAP+ eCAF subpopulations in tumour tissues of GC patients and in the TCGA database." (PMID 37199594, 2023). "Periostin (POSTN) is predominantly secreted by stromal fibroblasts to promote the proliferation of tumor cells." (PMID 37709737, 2023). "In this study, mCAFs (POSTN+) were found to be present in the invasive front of the tumor, primarily located within collagen-rich stromal streaks, indicating their association with tumor invasion." (PMID 36980203, 2023). "CAFs producing periostin promoted the maintenance of cancer stem cell niche, angiogenesis, tumour growth, invasion and metastasis." (PMID 38115703, 2023). "Is this study we found that POSTN inhibited apoptosis, which was firstly reported in neoplastic diseases." (PMID 37572219, 2023). "Lower periostin levels resulted in the inhibition of Iba1+ (tumor-promoting) macrophage infiltration of GBM xenografts." (PMID 36831214, 2023). "In this context, we investigated the necessity of Periostin, an extracellular matrix (ECM) protein associated with tumor promotion." (PMID 38139195, 2023). "Meanwhile, SPOCK1 and POSTN were enriched in a variety of immune-related pathways and were related to the regulation of tumor immune cells and the expression of multiple immune checkpoint genes." (PMID 36611136, 2023). "IHC evaluation in consecutive sections of CRC tumors performed by expert pathologist indicated that POSTN and FAP were expressed by tumor-associated fibroblasts, thus corroborating the POSTN expression by CRC CAFs reported in previous studies." (PMID 36765091, 2023). "Tumor cells, especially cancer stem cells, can also produce POSTN, which has been shown to regulate multiple biological behaviors of tumor cells, including proliferation, survival, invasion, angiogenesis, metastasis, and chemoresistance." (PMID 38076555, 2023). "The TAMs are primarily present in the tumor stroma, and POSTN encourages CD163+ macrophages to release various cytokines, including Treg-related chemokines (CCL17 and CCL22)." (PMID 37525217, 2023). "IHC analysis indicated that treated tumors displayed abundant stromal accumulation of POSTN compared to untreated tumor samples from the same patients." (PMID 36765091, 2023).